CD44 (CD44 molecule (IN blood group))
Diseases named in the same sentence as CD44 in open-access papers (continued):
Sharing a sentence is not in itself a finding about the gene and the disease.
cancer (continued). "In order to examine stemness-like features of SCEACono2 cells, the presence of cancer stem cell markers (CD44, CD133, Oct3/4, ALP) was examined." (PMID 37949965, 2023). "The interaction of HA and membrane receptor CD44 or Toll-like receptor 4 (TLR-4) sustains proliferation of cancer and the formation of fibrosis." (PMID 36906534, 2023). "With regards to changes in cancer stem cell markers, CD44 showed low levels after 5-fluorouracil administration." (PMID 37523119, 2023). "Many studies have reported that CRC cancer cells in spheroids express markers associated with stemness phenotypes such as CD133, CD44, CD44v6, CD166, and Lgr5, the latter widely used to study CRC cancer stem-like cells both in in vitro and in vivo models." (PMID 36982333, 2023). "Among the last, there are amphiphilic polysaccharide polymeric micelles, where HA can function both as a hydrophilic polymer forming the external part and as a ligand for targeting CD44 that is overexpressed on many cancer cells." (PMID 37376199, 2023). "CD44 is a protein surrounded by a membrane that is often highly expressed in various cancer cells and a major receptor for HA." (PMID 36826291, 2023). "We intended to develop a workable inflammation marker in cell-based liquid biopsy to predict malignancy based on a CD44-related circulating rare cell phenotype as an alternative to probe a perhaps more exposed aspect of cancer residual disease." (PMID 36100762, 2023). "CD44 is part of several pathways that were significantly different between the cancer cells and epithelial cells and between the cancer cells and redirected cells." (PMID 36765535, 2023). "Meanwhile, CD44 participates in metabolic regulation, inducing chemotherapy resistance by suppressing intracellular reactive oxygen species (ROS) in cancer cells." (PMID 38455361, 2023). "Of the stem cell markers, Sox9 expressed much higher in tumors than in normal tissues, and CD44 expressed higher in tumors as well, suggesting cancer stem cells were playing important roles." (PMID 36865791, 2023). "The authors conjugated HA into carbon nanotube composites to capture CD44 selectively in human serum and cancer cells." (PMID 37754116, 2023). "The TCF4 and AP-1 downstream gene CD44, a protein that is expressed on the cell surface in cancer stem cells, interact with PKM2, and thereby strengthen the glycolytic phenotype of hypoxic cancer cells." (PMID 37553596, 2023). "In this review, I will discuss the role of CD44 in cancer and highlight the potentially dichotomous function of the hyaluronan/CD44 axis in cancer treatment." (PMID 37958796, 2023). "CD44 on the surface of cancer stem cells can also contribute to resistance via specific receptor-mediated and anti-apoptotic mechanisms." (PMID 37958796, 2023). "Chemoresistance was correlated with cancer cell stemness in patients with CRC, and patients expressing the CD44 variant appear to present with more aggressive phenotypes of CRC." (PMID 36900159, 2023). "Synthesized SOXs (4a–h) were further subjected to the drug-likeness, ADME, and in silico screening for their inhibitory efficacy against cancer-specific molecular markers, i.e., CD44, AKR1D1, HER-2, and EGFR." (PMID 37108498, 2023). "We first examined the reactivity of C44Mab-94 in the OSCC tissue array because this type was revealed as the second highest CD44-positive cancer type in the Pan-Cancer Atlas." (PMID 37489367, 2023). "Hyaluronic acid (HA) receptor CD44 is widely used for identifying cancer stem cells and its activation promotes stemness." (PMID 37958796, 2023). "They proved that the modification of HA can enhance the targeting ability of nano-drug delivery system to CD44 overexpressed cancer cells." (PMID 37465582, 2023). "Because HNSCC has been revealed as the second highest CD44-expressing cancer type in the Pan-Cancer Atlas, we first examined the reactivity of C44Mab-1 and C44Mab-46 in an oral SCC tissue, as a positive tissue control." (PMID 37185762, 2023).
cancer (continued). "CD44 is a cell surface adhesion receptor that is abundantly present in numerous cancer types and regulates metastasis via the recruitment of CD44 to the cell surface and has been identified as a marker for different types of cells, including TSCs." (PMID 37894787, 2023). "The co-localization of hyaluronan and CD44 has been observed in various cancers and has been demonstrated to facilitate tumorigenesis." (PMID 37509716, 2023). "In our study, we confirmed the presence of cancer cells by assessing the expression of a group of CD44(+) and CD24(+) receptors." (PMID 38201547, 2023). "Common markers like CD44, CD133, and c-Kit, in conjunction with the WNT and Notch signaling pathways, are associated with cancer stemness activities." (PMID 38136437, 2023). "Accumulating evidence has demonstrated that CD44 alternative splicing frequently occurs during cancer progression." (PMID 36127291, 2023). "CD44 is a single-transmembrane glycoprotein and its role in cancer development has been widely reported." (PMID 37715221, 2023). "CD44 is often overexpressed on the surface of cancer cells and is viewed as a biomarker in many solid tumors." (PMID 37627173, 2023). "Among these adhesion molecules, CD44, a transmembrane glycoprotein, serves as the primary receptor of glycosaminoglycan hyaluronan, modulating migration/invasion during cancer progression." (PMID 37461792, 2023). "Different CD44’s isoforms are expressed in various cancer types, which serve as prognostic biomarkers and therapeutic targets." (PMID 38139340, 2023). "Concerning this problem in terms of CD44 expression, we are analyzing CD44 isoforms specifically expressed in GSC, as many cancer stem cells express specific CD44 isoforms and the isoforms thus represent biomarkers for each cancer." (PMID 37760811, 2023). "The CD133+/CD44+ population, which seems to be the most common for cancer stem cell identification, is the highest in the BR1 culture (14.2%)." (PMID 37998351, 2023). "Using hyaluronic acid as targeting moiety (targeting CD44 overexpressing cancer cells) makes it superior to both conventional therapy and stealth-technology based NPs, which are currently available in the market." (PMID 36679166, 2023). "Some CD44 isoforms, such as CD44v6 and CD44v9, have been found to be frequently expressed in many types of cancer, including pancreatic, colon, and prostate cancer." (PMID 37854601, 2023). "A huge amount of data indicates that different CD44 isoforms play a role in many types of cancer [reviewed in], and their cellular functions can both overlap and be distinct." (PMID 38106992, 2023). "They found that CD44 had a significantly higher expression in intramammary/intratumor areas compared with extramammary/extratumor areas in both benign and malignant tumors." (PMID 36899736, 2023). "CD44 is a cell surface adhesion receptor that is highly expressed in many cancers and participates in cell adhesion migration and metastasis." (PMID 38067141, 2023). "Here we report the results of the first-of-its-kind genome-wide analysis of mRNA-lncRNA co-expression networks in a CD133+/CD44+ PDAC cell subpopulation isolated by the highly aggressive cancer cell lines MIA PaCa-2 and PANC-1." (PMID 36831395, 2023). "An example would be CD44 on the seeding cancer cells and hyaluronic acid on the surface of ‘soil’, the peritoneum." (PMID 36614319, 2023). "As previous studies have reported that the acquisition of invasiveness in cancer cells is accompanied by stemness features, we analyzed the expression of CD44 and BMI-1, universal markers for stem cells, using qRT-PCR and western blot analysis." (PMID 38137388, 2023). "Collectively, these results revealed the difference in CD44 expression patterns between cancer and normal samples in the pan-cancer datasets." (PMID 37117249, 2023).
cancer (continued). "Compared to CD44− cancer cells, the CD44+ cancer cell population has a substantially higher osteogenic differentiation potential, as judged from the relative expression levels of all the analyzed osteogenic markers (p = 0.0001)." (PMID 36902135, 2023). "CD44 was the first cluster of differentiation molecule to be identified as CSC marker in human cancer disease, including HNSCC." (PMID 38003753, 2023). "This setup has the potential to be utilised in the creation of a theranostic approach that zeroes in on CD44-overexpressing cancer cells and CSCs." (PMID 37375846, 2023). "Cluster of differentiation 44 (CD44) is a type I transmembrane glycoprotein and has been shown to be a cell surface marker of cancer stem-like cells in various cancers." (PMID 37185762, 2023). "CD44 is also regarded as the most common stem cell surface marker in many cancers, such as those of the stomach, breast, lung, colon, and brain." (PMID 37835592, 2023). "CD44 participates in multiple cellular processes in cancers, including GBM, as not only an adhesion molecule but also a signal-transducing molecule." (PMID 37835592, 2023). "Some cancer stem cell markers have shown a positive correlation with the degree of dysplasia, including CD44, retinal dehydrogenase 1, prominin-1, and podoplanin." (PMID 37893561, 2023). "CD44 is a cell surface adhesion receptor, and is known as a cancer stem cell marker in several cancer cells." (PMID 36810561, 2023). "CD44 overexpression and its strong affinity to HA was recently explored in cancer targeting by developing nanoparticles that contain anti-tumoral drugs into which HA is incorporated." (PMID 37107200, 2023). "Considering that traditional cancer chemotherapeutic agents and radiotherapy cannot eradicate CSCs, the cytotoxicity of curcumin against CD44+ human prostate CSCs is a remarkable feature." (PMID 37663388, 2023). "This nanoplatform was smartly decorated with hyaluronic acid, a specific ligand for CD44, to achieve targeted delivery in the treatment of cancer." (PMID 36678599, 2023). "As a hyaluronic acid receptor, CD44 engages with multiple ligands, adeptly mediating intracellular interactions that activate cancer cell migration and metastasis." (PMID 38455361, 2023). "CD44 binds to various ligands and the interactions allow cancer cells to execute many cellular functions via the various signal transductions specific to the ligands." (PMID 37835592, 2023). "CD44 is capable of binding to HA, which provides a scaffold for cancer cells to adhere to and migrate through the extracellular matrix." (PMID 37958796, 2023). "Since miR-483 inhibits cell survival and migration, we also analyzed the effect of miR-483 on the expression of Nanog and CD44 cancer stem cell markers and oncogenic TNFα-Induced Protein 8 (TNFAIP8) marker." (PMID 36980601, 2023). "Although CD44 has been extensively studied in certain types of cancer, its role remains elusive in multiple cancers." (PMID 37117249, 2023). "Accordingly, the percentage of rare cell abnormality by quantity measured 80% and the frequency of CD44i35 fraction within CD44+ CRC (true-positive fraction) in each cancer cohort was significantly increased measuring on average 41.7%." (PMID 36100762, 2023). "A comprehensive analysis of malignant ascites identified the amplifications of cancer driver genes including CD44." (PMID 37489367, 2023). "For the treatment against refractory tumors, such as the recurrence after chemotherapeutic agents, the treatment should target the emerging specific population such as CD44 (or CD44v9) as well as proliferative cancer cells." (PMID 37523119, 2023). "Initially, we identified a significant co-expression pattern of KDM5 family members and the stem cell marker CD44 in various cancers by performing Spearman correlation analysis through the starBase V3.0 website." (PMID 37880235, 2023).
cancer (continued). "CD44 overexpression seems to be a conserved mechanism in cancer progression, as a meta-analysis suggested that positive CD44v9 expression predicted a worse prognosis in most human cancers." (PMID 37958796, 2023). "Our study demonstrated that CD44 shows great promise as a prognostic biomarker in numerous cancers, which will assist in developing new strategies in cancer management." (PMID 37117249, 2023). "In this research, we described the functional significance of CD44 and identified the differential expression of CD44 within cancers and normal tissues in 12 cancer types from the pan-cancer datasets." (PMID 37117249, 2023). "The CD44 receptor is highly expressed in many cancers and regulates metastasis via recruitment of CD44 to the cell surface." (PMID 37629139, 2023). "CD44 48, a marker of cancer stemness, was upregulated in the hypoxic control group and downregulated in the C4orf47- suppressed group compared with normoxia." (PMID 36741255, 2023). "Hyaluronic acid (HA)-based hydrogels have shown great potential in drug delivery and targeted cancer therapy since cellular membrane surface HA receptors like CD44 are upregulated in multiple cancer cells." (PMID 36750868, 2023). "RNAPII occupancy also mirrored that of NELF-E binding, as exemplified by cancer stem cell marker CD44 and mesenchymal gene FN1, both of which are upregulated upon Dox induction in control cells but curtailed in NELF-E KD cells." (PMID 37117180, 2023). "Sometimes, the information about the functions of CD44 isoforms is controversial, which complicates our current understanding of their roles in malignancy and cancer progression." (PMID 38106992, 2023). "CD44-targeted drug delivery systems can selectively transport therapeutics to cancers and CSCs while minimizing effects on normal cells." (PMID 38102651, 2023). "EMT results in the improvement of CD44-positive cancer stem cells, and in certain studies, EMT has been found to suppress the growth of stem cell-like features, which opposes the idea of EMT-induced stemness." (PMID 37012965, 2023). "In other research, CD44+ cancer stem-like cells can switch to EMT cells via TGFβ1-CD44 signaling and drive PCa metastasis." (PMID 36778124, 2023). "Cluster of differentiation 44 (CD44) is a transmembrane protein that is known to be overexpressed in various types of cancer cells." (PMID 37759771, 2023). "CD44, a widely accepted marker for cancer stem cells and a mesenchymal marker regulating both stemness and epithelial-mesenchymal plasticity, was shown to be predominantly upregulated in CEGBCs-DB." (PMID 37147437, 2023). "An enhanced antitumor effect of HA-mExo-miR204 was observed in vitro and in vivo when targeted specifically towards CD44-positive cancer cells." (PMID 38260737, 2023). "In EOC, CD44+ cancer stem cells are inherently chemoresistant and are epithelial in character, while their CD44- mesenchymal progeny are fast-dividing and therefore chemosensitive." (PMID 37568736, 2023). "The interaction between cancer stem cells (CSCs) and CD44 plays a crucial role in regulating various aspects such as cell survival, self-renewal, preservation, and resistance to chemotherapy." (PMID 37491225, 2023). "In conclusion, we developed a recombinant adenovirus vector, Ad-CD44-N-HIF3α4, containing a synNotch receptor gene which inhibited CD44 signaling and hypoxia-induced response in cancer cells." (PMID 37064130, 2023). "Phenotypic changes of mesothelial cells to CAMs are mediated by TGF-β and CD44 and annexin A2 secreted inside exosomes from cancer cells." (PMID 37448521, 2023). "Monitoring CD44 on CTCs in terms of detection and quantification can provide a significant improvement in clinical cancer diagnosis." (PMID 37754116, 2023). "CD44 is a cell surface molecule; it plays a significant role in cell proliferation, cell differentiation, cell migration, and angiogenesis in many cancer cells." (PMID 37376218, 2023).
cancer (continued). "HA specially binds and interacts with the cell surface receptor CD44, leading to cancer cell growth and survival." (PMID 37153732, 2023). "The increasingly common use of HA-conjugated drugs in oncology, as well as HA-based compounds as adjuvants in cancer treatment, adds further complexity to the understanding of the net effect of hyaluronan-CD44 activation in cancers." (PMID 37958796, 2023). "C4orf47 is transformed into Cancer Stem Cells (CSCs) like because it enhances CD44 expression and maintained a low p- Erk/p-p38 ratio, suggesting that it is involved in dormancy." (PMID 36741255, 2023). "In various cancers, including ovarian cancer, FDFT1 is associated with invasion and activates cancer cell metastasis through MMP1, CD44, and AKT/mTOR/HIF1α signaling." (PMID 37107644, 2023). "For active targeting of virus loaded nanoformulation against CD44 (cluster of differentiation 44) receptors which are overly expressed on cancer cells, these nanoparticles were surface functionalized with hyaluronic acid (HA)." (PMID 37283735, 2023). "The dissociation free energy profiles obtained by US simulations indicated that oxidation of both CD44 and HA weakened their interaction, thereby inhibiting the signaling pathways of cancer cell proliferation." (PMID 37759771, 2023). "Because CD44 is also overexpressed on certain cancer cells, HA is being researched as a component of drug delivery systems for both the treatment of infections and cancer." (PMID 37895831, 2023). "Among these broad implications in cellular processes, CD44 represents also a common cancer stem cell marker and is highly expressed on many different cancer cells." (PMID 36876041, 2023). "Many kinds of cancer cells are known to overexpress CD44 in comparison to normal cells, indicating its relevance as a potential therapeutic target in cancer." (PMID 37111795, 2023). "The pleiotropic roles of CD44 in carcinoma offer new molecular targets for CD44-targeted therapy for cancer management." (PMID 37593530, 2023). "CD44 is a transmembrane glycoprotein expressed in various cells, such as embryonic stem cells, differentiated cells and cancer cells, including GBM." (PMID 37760811, 2023). "Hyaluronic acid (HYA) is well known as a CD44-targeting ligand and has frequently been used to decorate the nanoparticle surface for delivery to CD44-overexpressed cancer cells owing to its specificity toward CD44 receptors." (PMID 37376218, 2023). "We found higher levels of epithelial stem cell/cancer stem cell markers (e.g., Lgr5, Axin2, Cd44, Prom1/CD133) in the tumoroids derived from ApcMin/+ WT as compared with ApcMin/+ Stat2−/− mice." (PMID 38001683, 2023). "CD44 expression is upregulated in cancer cell subpopulations and serves as a molecular marker of CSCs." (PMID 37853413, 2023). "We investigated the utility of CD44 in evaluating therapeutic responses of targeted therapy to various cancer." (PMID 37117249, 2023). "In the clinical trial, NCT01424865, the expression of the cancer stem cell biomarker CD44+/CD24− y ALDH1 was evaluated as a predictor of response to Trastuzumab in 1874 samples from BC patients previously treated in the NSABP-B-31 trial." (PMID 36899854, 2023). "First, CD44 interacts with HA in the extracellular matrix, promoting cancer cell adhesion and invasion, which can shield cancer cells from the cytotoxic effects of chemotherapy drugs." (PMID 37958796, 2023). "Cluster of differentiation 44 (CD44) is the main HA receptor and is also one of the markers for cancer stem cells." (PMID 37759706, 2023). "One mechanism by which the hyaluronan/CD44 axis promotes cancer is through its involvement in cell adhesion and migration." (PMID 37958796, 2023). "Gal-9 has direct cytotoxic effects, binds to CD44 expressed on cancer cells to limit cancer metastasis, and enhances the stability and function of adaptive regulatory T cells." (PMID 38328306, 2023).